PRAMEF27 (PRAME family member 27)
Tractability: No criterion of Open Targets' tractability assessment is met for any kind of drug.
Gene: Protein-coding gene on chromosome 1 (13,049,476 to 13,056,575, reverse strand). Ensembl gene ENSG00000274764.
Gene Ontology:
Molecular function: ubiquitin-like ligase-substrate adaptor activity
Biological process: proteasome-mediated ubiquitin-dependent protein catabolic process; negative regulation of apoptotic process; negative regulation of cell differentiation; negative regulation of DNA-templated transcription; positive regulation of cell population proliferation
Cellular component: Cul2-RING ubiquitin ligase complex; cytoplasm
Genetic constraint (gnomAD): Loss-of-function variants: 4 observed, 9.74 expected, observed/expected ratio (o/e) 0.41, 90% interval 0.2 to 0.94. That is too few expected variants to judge how well the gene tolerates losing a copy. Missense variants: 124 observed, 180.67 expected, observed/expected ratio (o/e) 0.69, 90% interval 0.59 to 0.8. Synonymous variants: 57 observed, 73.58 expected, observed/expected ratio (o/e) 0.77, 90% interval 0.62 to 0.97.
Homologues: Orthologues: mouse Pramel13 (45% identical), rat Pramef12 (44% identical), rat Pramef8 (43% identical), mouse Pramel12 (43% identical), mouse Pramel15 (43% identical), rat LOC120103107 (43% identical), rat Pramef5 (42% identical), mouse Pramel31 (42% identical), mouse Pramel16 (42% identical), mouse Gm13040 (42% identical), mouse Gm13043 (42% identical), mouse Gm13057 (42% identical), and 78 more. Paralogues in human: PRAMEF9 (99% identical), PRAMEF15 (97% identical), PRAMEF6 (96% identical), PRAMEF5 (96% identical), PRAMEF25 (96% identical), PRAMEF26 (96% identical), PRAMEF4 (95% identical), PRAMEF11 (95% identical), PRAMEF20 (80% identical), PRAMEF12 (62% identical), PRAMEF8 (61% identical), PRAMEF7 (61% identical), and 12 more.